SNORD52 (small nucleolar RNA, C/D box 52)
Synonyms: U52; RNU52
Gene: Small nucleolar RNA gene on chromosome 6 (31,837,076 to 31,837,142, forward strand). Ensembl gene ENSG00000201754.
Gene Ontology:
Biological process: RNA processing
Cellular component: nucleolus
Homologues: Orthologues: chimpanzee SNORD52 (100% identical), macaque SNORD52 (99% identical), guinea pig SNORD52 (88% identical), rat Snord52 (82% identical), mouse Snord52 (81% identical).
Diseases named in the same sentence as SNORD52 in open-access papers:
SNORD52 is named in the same sentence as 2 diseases in open-access papers, as found by Europe PMC text mining. Sharing a sentence is not in itself a finding about the gene and the disease. The quoted sentences say what the papers report.
hepatocellular carcinoma (3 papers, 2021 to 2022). A malignant tumor that arises from hepatocytes. "In addition, upregulated SNORD52 drives tumorigenesis via the Upf1/SNORD52/CDK1 pathway and may serve as a biomarker to predict poor prognosis for hepatocellular carcinoma." (PMID 34702132, 2021).
SNORD52 also shares sentences with these, for which no sentence is quoted: infection (1 paper).